INS (insulin)
Diseases named in the same sentence as INS in open-access papers (continued):
Sharing a sentence is not in itself a finding about the gene and the disease.
diabetes (continued). "CD1D is a transmembrane protein involved in the presentation of lipid antigens to T cells and known to contribute to the generation of diabetes, and PSD belongs to a family of intracellular signal transduction proteins known to increase insulin sensitivity." (PMID 19961616, 2009). "Sub-network from obesity and diabetes datasets indicate the significant roles of SUMO4, GAPDH and EGFR interactions in insulin signalling diabetes progression." (PMID 19997558, 2009). "Lower levels of SRH were associated with worsened levels of inflammatory markers, blood lipids, insulin and insulin resistance in both the total population and a sub sample free from CVD, diabetes and cancer." (PMID 19788754, 2009). "In addition to Type 1 diabetics, who produce insufficient insulin, and Type 2 diabetics, who are unable to effectively use the insulin they produce, a third type of diabetes may be environmentally exacerbated or induced by exposure to electromagnetic frequencies." (PMID 18568931, 2008). "SGK is an attractive candidate gene for type 2 diabetes mellitus onset in humans, as SGK1 exerts pleiotropic effects on glucose metabolism and insulin secretion in various cellular and animal models." (PMID 18985156, 2008). "Although 85% of the patients were on insulin infusions for tight blood glucose control during their ICU stay, only 17 patients had preexisting diabetes mellitus." (PMID 19742269, 2008). "Insulin, familiar to many only as a medication used in the treatment of diabetes, is a very anabolic compound that shuttles needed nutrients to muscles, produces growth factors when combined with HGH in the liver and combats insulin resistance produced by HGH." (PMID 17931410, 2007). "At follow-up, GDM women who developed diabetes had larger body mass index (BMI), waist-to-hip ratio (WHR) and sum of skinfolds, were more insulin resistant, and had significantly lower insulin increment than IGT/IFG and NGT women." (PMID 17640759, 2007). "Medical literature suggests that well controlled biochemical and genetic studies are required to establish the link between insulin, IGF-1, diabetes and cancer." (PMID 17953765, 2007). "In contrast, genes involved in lipid and amino acid pathways, ubiquitin mediated proteolysis, signal transduction, insulin signaling and PPAR signaling pathways are downregulated in subjects with diabetes with family history of diabetes." (PMID 18078524, 2007). "Insulin is the drug of choice in the management of diabetes mellitus (DM)." (PMID 16448577, 2006). "Diabetes Mellitus (DM) is a metabolic disorder of multiple etiologies characterized by chronic hyperglycemia with disturbances of carbohydrate, fat and protein metabolism resulting from defects in insulin secretion, insulin action or both." (PMID 17187674, 2006). "Diabetes mellitus (DM) is characterized by chronic hyperglycemia due to insufficiency of insulin." (PMID 12395879, 2002). "Cumulative incidence curves illustrate that, following a type 2 diabetes diagnosis, participants with SMI were prescribed both metformin and insulin sooner after diagnosis of diabetes than those without SMI." (PMID 41235789, 2026). "Diabetes mellitus is characterized by the absence of insulin secretion, often partially at the time of diagnosis and completely within months or a few years afterwards." (PMID 41597086, 2026). "Diabetes mellitus is typically the first manifestation, presenting at a mean age of 6 years as an insulin-dependent phenotype with preserved C-peptide and negative diabetes-related autoantibodies." (PMID 41959758, 2026). "In total, 7 individuals in our cohort exhibited prolonged periods without insulin treatment: 3 are currently treated with sulphonylurea and 4 had transient diabetes." (PMID 41500078, 2026).
diabetes (continued). "Fasting insulin was more than 15-fold higher in T2DM (median 49.82 μU/mL) compared with PreDM (3.28 μU/mL), resulting in significantly higher HOMA-IR and lower QUICKI indices (p < 0.0001), confirming severe insulin resistance in newly diagnosed diabetes." (PMID 41596434, 2026). "Rapid reduction of glucose with intensive diabetes therapy has previously been demonstrated to lead to a transient worsening of diabetic retinopathy with GLP-1 and insulin; additionally, the concept of ‘insulin neuritis’ is rather similar, linked to a rapid decline in hyperglycemia." (PMID 41523719, 2026). "Diabetes mellitus is a chronic disease that affects humans and is generally characterized by high blood glucose levels, either due to a lack of insulin or the body’s resistance to insulin." (PMID 41495252, 2026). "Clinical features of MODY largely overlapped with non-MODY diabetes either treated with insulin from diagnosis or not." (PMID 41288518, 2026). "A suitable encapsulation device and/or immunomodulated cells having the ability to regulate insulin secretion without immunosuppression would pave the way for an effective and reliable therapy to reverse diabetes." (PMID 41597265, 2026). "In individuals without diabetes, a decline in endogenous insulin secretion (from β cells) and a rise in glucagon secretion (from α cells) limit hypoglycemia when blood glucose levels decline to approximately 3.5 mmol/L." (PMID 41502124, 2026). "Additionally, in a US pilot study of patients with T2D using non-insulin therapies, significant increases in healthy eating were reported with the use of CGM alongside diabetes self-management education." (PMID 41601933, 2026). "Protein ingestion normally stimulates alpha and beta cells to produce glucagon and insulin, respectively in people not living with diabetes." (PMID 41602572, 2026). "Continued innovation in sensor accuracy, automated insulin delivery, and data analytics-combined with improved access and equitable reimbursement-will be essential to fully realize the potential of CGM for the growing global diabetes population." (PMID 42306173, 2026). "For example, in the treatment of Type 2 Diabetes Mellitus (T2DM), combining BBR with Metformin may lead to more pronounced effects on insulin sensitivity and glucose metabolism, resulting in better blood glucose control." (PMID 41596399, 2026). "Diabetes treatments favoured metformin and DPP-4 inhibitors; 5.2% received insulin." (PMID 41598511, 2026). "We explored R6C pathogenicity using integrative clinical, genetic, and functional approaches.Homozygous INS R6C individuals presented early-onset insulin-treated diabetes, whereas heterozygous carriers showed variable or absent glycemic phenotypes." (PMID 41484206, 2026). "Nearly half had diabetes for over 10 years (49%), and notably, most of them were not using insulin (58.3%)." (PMID 41311517, 2026). "The Success with Individualized Insulin Management (SWIIM) program, developed at John Hunter Children's Hospital (JHCH) in New South Wales (NSW), Australia, has demonstrated glycemic outcomes among the best reported nationally for pediatric diabetes." (PMID 41970987, 2026). "Type 2 diabetes mellitus (T2DM) is a highly prevalent (>400 million patients worldwide) metabolic disorder characterized by chronically elevated blood glucose resulting from systemic insulin resistance and impaired insulin secretion." (PMID 40551391, 2026). "Diabetes mellitus was identified in 21.2% (7.4% non-insulin-dependent and 13.8% insulin-dependent), although data were unavailable for 78.8% of the cohort." (PMID 41576058, 2026). "At baseline, 30 % of patients newly initiated on insulin therapy at our institution did not receive appropriate diabetes-related prescriptions upon hospital discharge in 2019." (PMID 41551323, 2026). "Managing diabetes entails lifelong control using oral anti-diabetic drugs (OAD) and insulin." (PMID 39792998, 2026).
diabetes (continued). "The demands of managing type 1 diabetes mellitus (T1DM) throughout life, such as administering insulin, monitoring blood sugar, controlling nutrition, and fear of both acute and long-term complications, exacerbate these developmental difficulties for teenagers." (PMID 41924671, 2026). "All children with diabetes used a CGM sensor, five at baseline and two at 2 year follow-up were treated with a multiple injection regimen, and 45 at baseline and 26 at follow-up had continuous insulin infusion using an insulin pump." (PMID 41219438, 2026). "Regardless of the type of diabetes, including mitochondrial diabetes, when edema develops after a rapid improvement in hyperglycemia induced by insulin, insulin edema should be considered in the differential diagnosis." (PMID 41476905, 2026). "Type 2 diabetes mellitus (T2D) occurs when the body produces low insulin, but the cells do not respond to it properly—a condition known as insulin resistance." (PMID 41495252, 2026). "Unlike channelopathies, these forms of diabetes are typically insulin-dependent and do not respond to sulfonylureas." (PMID 41614934, 2026). "The prevalence of diabetes in our study was 15.23%, which is higher than the prevalence of insulin (0.22%) and non-insulin (1.26%) dependent diabetes found among refugees in Greece." (PMID 41602018, 2026). "contributes to epithelial barrier protection, supports maintenance of the mucus layer, and improves metabolic disorders (such as diabetes) through multiple mechanisms, including stimulation of glucagon-like peptide-1 (GLP-1) secretion by intestinal L cells, which promotes insulin production." (PMID 41505413, 2026). "Background/Objectives: To investigate how β-cell glucose sensitivity, insulin clearance, and insulin sensitivity interact to determine glucose tolerance in a population without overt diabetes." (PMID 42042863, 2026). "Research indicates that the incretin effect accounts for approximately 50% of insulin secretion in individuals without diabetes, which is significantly reduced to 30% or less in those with Type 2 Diabetes Mellitus (T2DM)." (PMID 42091853, 2026). "Individuals with ZNF808-diabetes did not always require insulin treatment, with sulphonylurea treatment reported in 3 individuals." (PMID 41500078, 2026). "Effects on glucose control were similar irrespective of sex, prior insulin therapy, body mass index, and diabetes duration, but varied in relation to glucose control." (PMID 41917055, 2026). "At the core of these effects lies brain insulin resistance (BIR), a disruption in insulin signaling within the central nervous system that can occur even in individuals without diabetes." (PMID 40819304, 2026). "High-quality evidence suggested a reduced risk of progression from monoclonal gammopathy of undetermined significance to multiple myeloma among US veterans with diabetes on GLP-1 RA therapy, and a lower incidence of multiple myeloma among GLP-1 RA users compared to insulin users." (PMID 41583363, 2026). "Insulin for youth in Tanzania and Bangladesh are typically donated by manufacturers – Eli Lilly and Novo Nordisk, through the Life For A Child (LFAC) and Changing Diabetes in Children (CDiC) programs, respectively." (PMID 41481625, 2026). "Latent autoimmune diabetes in adults (LADA) is frequently misdiagnosed as type 2 diabetes mellitus (T2DM), particularly in older adults, owing to its adult onset, initial insulin independence, and indolent clinical course, resulting in the delayed initiation of insulin therapy." (PMID 41777958, 2026). "In one diabetes GMV, many patients used insulin, which can only be taken by daily injections." (PMID 39680019, 2025). "Tigecycline-induced hypoglycaemia can happen in patients with or without diabetes and develop independent of insulin or antidiabetic drugs." (PMID 40386810, 2025).
diabetes (continued). "Using the principles of ‘sick day rules’, non-insulin medicines for diabetes mellitus should be stopped and restarted when the person is well (normally after 24–48 h of eating and drinking normally)." (PMID 40651878, 2025). "In a randomized controlled trial of 35 healthy postmenopausal women without diabetes, those receiving metformin experienced a 19% reduction in free testosterone compared with placebo, alongside expected improvements in insulin sensitivity." (PMID 40443457, 2025). "The 1990 study included 60 diabetic patients (32 females and 28 males) with an average age of 46.8 ± 11.8 years, comprising both insulin-dependent and non-insulin-dependent individuals, with an average diabetes duration of 8.6 ± 4.6 years." (PMID 39996975, 2025). "Most participants did not have diabetes and as such were not on metformin, glucagon-like peptide-1 agonists, or other medications including insulin or sodium glucose transporter 2 inhibitors." (PMID 41245157, 2025). "Laboratory findings in this patient confirmed no diabetes medication use, with suppressed insulin (7.17 μIU/mL) and C-peptide (0.09 ng/mL) levels, consistent with NICTH." (PMID 41367853, 2025). "Limitations include that study results are only applicable to patients with prediabetes or diabetes not prescribed insulin, patients of the KPSC healthcare system, and those who had email addresses and telephone numbers available in the EHR." (PMID 41254652, 2025). "Additionally, based on the insulin data obtained in this study, the insulin level was always downregulated significantly and considerably, implying that the fentanyl and cocaine polydrug might have a stronger cardiovascular toxicity to the patients with insulin resistance and diabetes." (PMID 40076960, 2025). "This increase occurs when the body does not produce a sufficient amount of insulin, leading to type 1 diabetes mellitus, or when the body is unable to effectively use the amount of insulin produced by the pancreas, leading to type 2 diabetes mellitus (DM2)." (PMID 40003508, 2025). "According to previous reports, malnourished patients with type 2 diabetes mellitus (T2DM) exhibit elevated levels of glycated hemoglobin (HbA1c), random blood glucose (RBG), insulin, and glucagon, likely due to reduced insulin sensitivity and increased insulin resistance." (PMID 40469675, 2025). "believing that taking insulin meant patient had failed to manage their diabetes with oral hypoglycaemic agents - 48.7%)." (PMID 40336418, 2025). "Type 2 diabetes mellitus (T2DM) is a chronic medical condition characterized by persistently elevated blood sugar levels, occurring when the pancreas either cannot produce enough insulin or the body cannot utilize insulin effectively." (PMID 41523497, 2025). "For decades, diabetes was entrenched within a metabolic paradigm, reinforced by therapeutic success with insulin and the lack of tools to explore immune mechanisms." (PMID 40725617, 2025). "The high prevalence of T2D in the 45–49 year age group may be related to an age-related decline in insulin sensitivity; consequently, there is a close interaction between polycystic ovary syndrome (PCOS), uterine cancer, and type 2 diabetes mellitus." (PMID 40718420, 2025). "They found that obese individuals, both with and without diabetes, exhibited increased insulin secretion (hypersecretion), whereas in diabetic patients, regardless of weight, insulin secretion was significantly impaired." (PMID 41283270, 2025). "While detailed psychosocial data were limited in the charts, documentation frequently cited financial barriers, irregular access to insulin, and lack of structured diabetes education as contributing factors." (PMID 40755641, 2025). "Although we evaluated clinical variables such as age, diabetes duration, and insulin therapy type, these did not retain statistical significance in the final models." (PMID 40217883, 2025).
diabetes (continued). "Although the extra-islet insulin-positive cells were often present, they were reduced compared to donors without diabetes." (PMID 38922355, 2025). "We used mathematical modeling with data from 79 countries to estimate how newer diabetes medications (GLP-1 receptor agonists and SGLT-2 inhibitors) could affect insulin use and health outcomes." (PMID 40245017, 2025). "In contrast, the diabetes groups exhibited decreased β-cell function, which failed to adequately compensate for reduced insulin sensitivity or increased insulin resistance." (PMID 40361840, 2025). "In 2019, six years after the diagnosis of diabetes, the etiological assessment demonstrated a residual insulin secretion with random non-fasting C-peptide at 222 pmol/L (reference range > 200) and the absence of islet autoantibodies." (PMID 40290321, 2025). "Diabetes mellitus (DM) is an endocrine disorder characterized by either the lack of insulin (in type-1 DM) or the development of insulin resistance (in type-2 DM)." (PMID 40751579, 2025). "In addition, the prevalence of diabetes in the POD group was significantly higher (48.28% vs. 28.66%, p = 0.037), and the proportion of insulin or other hypoglycemic drugs was also higher (44.83% vs. 24.84%, p = 0.028)." (PMID 41018204, 2025). "Previously diabetes was classified along therapeutic lines, as either insulin-dependent or non-insulin dependent diabetes." (PMID 40244115, 2025). "We were also unable to evaluate the degree of control of relevant comorbidities, such as hypertension or diabetes, as key clinical parameters (e.g., HbA1c, insulin dosage, lipid values) were not systematically documented in a retrievable format." (PMID 40806909, 2025). "The extraordinary sample distribution of orexin A in our COVID-19 cohort was not dependent on sex, age, BMI, glucose, insulin, cardiovascular disease, obesity, or diabetes mellitus." (PMID 40529720, 2025). "Amongst the oral hypoglycemic drugs, sulfonylurea and the glinide group have been regarded as insulin secretagogues; however, due to hypoglycemia and other side effects, these drugs are not considered as the first choice of treatment for diabetes." (PMID 40564164, 2025). "In pregnant women with no prior history of diabetes who present with marked hyperglycemia (≥288 mg/dL) but relatively low HbA1c levels (<8.7%), fulminant type 1 diabetes should be suspected, and insulin therapy should be initiated immediately." (PMID 40650275, 2025). "The female partner (Patient A; no diabetes) sought weight loss therapy; the male partner (Patient B) had long-standing T2DM managed with insulin." (PMID 41211573, 2025). "The aim of the present report was to determine the association of a broad range of circulating sphingolipid species with measures of insulin sensitivity and insulin secretion in individuals without diabetes." (PMID 40630937, 2025). "Diabetes is a long-term health condition in which the pancreas either fails to produce enough insulin or the body is unable to use the insulin effectively." (PMID 41280964, 2025). "Initial targeted sequencing of neonatal diabetes-associated genes (including KCNJ11, ABCC8, INS, and the 6q24 locus) yielded negative results." (PMID 41393705, 2025). "Type 1 diabetes mellitus (T1DM) is an autoimmune disease that predominantly affects children and adolescents, leading to the destruction of pancreatic beta cells and resulting in an inability to produce insulin." (PMID 41185072, 2025). "Prediabetic and diabetic subjects were insulin-resistant compared to non-diabetic subjects, but only those with diabetes had significant reductions in their insulin production." (PMID 40218874, 2025). "Diabetes is defined as a chronic condition that arises when the pancreas fails to produce sufficient insulin or when the body is unable to effectively use the insulin it does produce." (PMID 41227648, 2025).